PTCH1 (patched 1)
Diseases named in the same sentence as PTCH1 in open-access papers (continued):
Sharing a sentence is not in itself a finding about the gene and the disease.
tumor (continued). "Our group has previously shown that stromal activation of canonical Hh signaling by genetic loss of Ptch1 in colonic stromal cells can attenuate tumor growth in a chemically induced colorectal tumor model." (PMID 33498528, 2021). "Patient P18 presents in each tumor a different selected variant but both in PTCH1 and both are considered as involved in BCC." (PMID 34284772, 2021). "On the other hand, patient P15 presents in each tumor different variants, of which a variant in PTCH1 and another in SMO are considered as responsible for BCC in the first and second tumors, respectively." (PMID 34284772, 2021). "PTCH1 is a tumor suppressor gene and its downregulation causes the activation of GLi transcription factors that activate the hedgehog target genes." (PMID 32523911, 2020). "We expected that the increase of proliferation of GCPs observed in the EGL of Ptch1+/+/Btg1KO mice at P7 caused by Btg1 deletion would lead in Ptch1+/−/Btg1KO cerebella to an increase of Ptch1+/− cells, which are prone to tumor development." (PMID 32231994, 2020). "Inactivation of PTCH1 through mutations confers Sonic Hedgehog independent growth, genomic instability and tumor development potential." (PMID 32409749, 2020). "The activity of vismodegib, in refractory metastatic medulloblastoma, was first reported in a patient whose tumor harbored a somatic mutation of PTCH1, thus activating the Hh signaling pathway." (PMID 31035664, 2019). "Though PTCH1 and B2M gene mutation correlates with the tumor growth, but it needs more proof to check the underlying mechanism between B2M mutation and the resistant response." (PMID 31692284, 2019). "The primary tumor sample with the D850V mutation in PDGFRB had concurrent mutations in PTCH1 (c.961C > A), ATR (c.4704C > G), and CDKN1A (c.419_420delGA)." (PMID 31480474, 2019). "Using their model, the team confirm that PTCH1 mutation activates tumour-associated signalling, which the basal cell carcinoma drug vismodegib greatly reduces." (PMID 30610186, 2019). "Overall, these results suggest that enhanced Wnt/β–Catenin signaling is responsible for cartilage/bone growth defects and tumor development caused by Ptch1 deficiency in MSCs." (PMID 31482846, 2019). "Here, we identified two cases of plexiform fibromyxoma (PF) with genomic loss of PTCH1, a tumor suppressor gene in the hedgehog pathway." (PMID 31362756, 2019). "In BCC, coincidental high expression of PTCH1 and GLI1 is only seen in tumours expressing a mutated PTCH1 allele that is ineffective at suppressing the HH pathway." (PMID 30068568, 2018). "In mice, heterozygous loss of Ptch1 in CD1 mice is associated with a 9% incidence of tumours resembling the embryonic subtype of RMS (ERMS)." (PMID 30068568, 2018). "The identification of PTCH1 loss as a therapeutic target presented a conundrum—because it is deleted from tumour cells, how does one target an absence?" (PMID 30068568, 2018). "Germline loss of one copy of PTCH1 is complemented by somatic mutation, or silencing, of the remaining allele in tumour cells, revealing that PTCH1 acts like a classic tumour suppressor gene in BCC and MB." (PMID 30068568, 2018). "This cell line has been established from an irradiation-induced tumor in a Ptch1+/- mouse, and has subsequently undergone Ptch1 loss of heterozygosity." (PMID 29869097, 2018). "Instead, Ptch1+/− mice are viable, although predisposed to low incidence of spontaneous tumor in several tissues/organs, including the brain." (PMID 29875630, 2018). "An inactivating mutation of PTCH1 on exon 21 was seen in the tumor DNA, which definitively proved the SHH subtype in one tumor (case 11)." (PMID 26857864, 2016).
tumor (continued). "Following the loss of one Ptch1 allele, Gli1 expression increased significantly in tumour tissue, whereas the effect in normal mucosa was less pronounced, probably reflecting background Hh activity in homeostasis." (PMID 27492255, 2016). "We identified a heterozygous mutation in PTCH1 (NM_000264.3:c.3944C>T) in the genomic DNA extracted from the blood, from the primary tumor and from a metastasis." (PMID 27825128, 2016). "Gene expression alteration is an important event in tumor cells and mutations in the patched 1 gene are frequently present in BCCs." (PMID 27578920, 2016). "Nevoid basal cell carcinoma syndrome (NBCCS) is a rare autosomal dominant disorder that is due, in large measure, to aberrant Shh signaling driven by mutations in the tumor suppressor gene Ptch1." (PMID 26413810, 2015). "While Gorlin syndrome is an inherited autosomal dominant disorder that causes loss of the tumor suppressor gene PTCH1, it only facilitates tumor development if the function of the other allele is disrupted." (PMID 26343726, 2015). "Humans with NBCCS inherit a germline mutation in one allele of the Ptch1 gene and tumor development is generally accompanied by loss of the remaining wild-type allele leading to aberrant activation of Shh signaling that drives the growth of these lesions." (PMID 26413810, 2015). "In our analysis, the tumor that harbored the PTCH1 P681L mutation expressed GLI1 at a level that was greater than six standard deviations above the mean, and was therefore clearly an outlier." (PMID 24368541, 2013). "Based on this functional defect and the marked elevation of GLI1 expression in the tumor, we conclude that PTCH1 P681L is likely to be a driver mutation." (PMID 24368541, 2013). "The formation of RMS in Ptch1-mutant mice has been associated with the ability of tumour cells to resist apoptosis." (PMID 22550422, 2012). "In a small subset of the brain, skin and muscle tumours, mutations in PTCH1 or SMOH trigger ligand-independent activation of the Hh pathway." (PMID 22361633, 2012). "Subsequent functional analyses and results from in situ studies of GCPs in postnatal cerebellum allowed us to formulate a model for the tumor promoting role of Nos2 deficiency in Ptch1 mutant mice via deregulation of Gap43-dependent migration of GCPs." (PMID 22438824, 2012). "Several mechanisms have been described that lead to the activation of the Hh signaling pathway in tumor cells, such as activating point mutations of Smo or inactivating point mutations in Ptch1 or SUFU." (PMID 21235817, 2011). "Ptch1, an inhibitory component of Shh signaling, acts as a tumor suppressor and germ-line mutations in Ptch1 promote MB formation in both humans and mice." (PMID 21437245, 2011). "We found that tumor tissues in the high-risk group for metastasis expressed lower levels of PTCH1 mRNA than did those in the low-risk group." (PMID 20230186, 2010). "In the Hh signaling pathway, Ptch1 is regard as the primary regulator, but the concurrent loss of both Ptch1 and Ptch2 results in more severe tumorigenesis than the loss of Ptch1 alone, highlighting the cooperative role of these two proteins in tumor suppression." (PMID 39900571, 2025). "Following the observation of a high G4 burden in the Ptch1 locus, we hypothesized that other tumor variant breakpoints would significantly overlap with putative G4 loci in MBs." (PMID 40854122, 2025). "The genetic background hosting the Ptch1 mutation can dramatically alter the individual risk for developing tumors, and this incomplete mutation penetrance suggests that other signaling molecules cooperate with Shh to enhance tumor formation." (PMID 39594660, 2024). "We hypothesised that this novel function could contribute to the tumour suppressor functions of PTCH1 and searched for evidence of somatic mutations in cancer that only affect this domain." (PMID 36672319, 2023). "Ptch1+/− heterozygous knockout mice are a model of tumor predisposition." (PMID 37175984, 2023).
tumor (continued). "Basal cell nevus syndrome (BCNS), or Gorlin syndrome, is a rare autosomal dominant disorder caused by mutations in the tumor suppressor gene PTCH1 with complete penetrance and variable expressivity characterized by a broad spectrum of developmental anomalies and a predisposition to neoplasms." (PMID 37752108, 2023). "Patient 29 acquired the PTCH1:p.G17del mutation during the process of tumor progression." (PMID 37533228, 2023). "The eccentrically high mutational abundance of the private PTCH1:p.G17del may represent the supplementary role of TISF cf-tDNA for tumor tissues." (PMID 37920153, 2023). "Notably, the PTCH1 mutation was correlated with tumor mutational burden (TMB), loss of heterozygosity score, and copy number variation burden." (PMID 34028566, 2022). "In order to establish the Hh signaling-related tumor model, we disrupted the wild-type PTCH1 allele remaining in three NBCCS-derived iPSC lines, G11-iPSC, G36-iPSC, and G72-iPSC, by introducing the CRISPR/Cas9 expression vector, which targets the wild-type PTCH1 sequence." (PMID 35618979, 2022). "The aim of the novel phase 2 study on taladegib, currently awaiting recruitment, is to evaluate the efficacy and safety in patients with loss of function of PTCH1 and advanced solid tumours based on occurring adverse events (AEs) and Response Evaluation Criteria in Solid Tumours (RECIST1.1)." (PMID 36291078, 2022). "The HGWG group propose expert recommendations (not of proven evidence) that are similar to those previously published for GS associated with PTCH1 PV, but the updated analysis of tumor risk associated with SUFU PV led to refined recommendations for screening for these patients." (PMID 33860896, 2021). "In our previous study, we found that patients with tumours showing low or negligible levels of the PTCH1 protein, were at increased risk of developing a local recurrence; this group of patients may benefit from adjuvant therapies using Hh inhibitors." (PMID 34480080, 2021). "OKC was classified as a tumor by the World Health Organization from 2005 to 2017 because of its high relapse rate, invasiveness, presence of epithelial dysplasia, and the recognition of gene mutations in tumor markers such as PTCH1 and Ki-67." (PMID 34195904, 2021). "This additional activation of SMO receptors (together with the mutated PTCH1 or SMO genes) could improve the tumour’s ability to resist some of the inhibition caused by Vismodegib, explaining the high GAS1 levels in the partially responsive laBCCs." (PMID 31988301, 2020). "It should be noted that we only detected somatic PTCH1 mutations in patients who had a germline mutation in that gene, suggesting that allelic instability leads to somatic mutations in the wild allele, promoting normal tissue progression to tumor tissue." (PMID 30754660, 2019). "Mutation of the PTCH1 gene may function as the turning point from tumor suppressor to drug transporter." (PMID 31704974, 2019). "The cancer samples with mutated PTCH1 had a lower number of tumor-infiltrating lymphocytes." (PMID 31704974, 2019). "The authors speculated that the acquired loss of the PTCH1 mutation in the setting of this oncogenic mutation probably promoted tumor regrowth under vismodegib in their patient." (PMID 29515801, 2018). "However, as we find that Ptch2 has a very limited ligand-perceiving role in BCC, we assume that its main function as a tumor suppressor is overshadowed by the loss of Ptch1, which is a stronger inhibitor of the Hh pathway." (PMID 29869097, 2018).
tumor (continued). "Interestingly, significant associations were observed between high Ptch1 and Gli1 expression with large tumor size, locoregional progression, and an incomplete response to chemotherapy." (PMID 30110910, 2018). "FISH analysis revealed hemizygous loss of PTCH1 in tumor cells." (PMID 29050204, 2017). "For example, mutation in PTCH1, a gene regulating cell proliferation, was present in tumor BC_1L." (PMID 27383411, 2016). "The LOH analysis of tumor DNA showed Ptch1 biallelic loss in all tumor samples." (PMID 26452034, 2015). "This indicates that both Ptch1 alleles were disrupted in the tumours." (PMID 26067104, 2015). "Importantly, Huwe1 is strongly down regulated in tumor-prone Ptch1+/− heterozygous mice, and low HUWE1 expression is associated with poor prognosis only within the SHH subgroup of human MB." (PMID 25008045, 2014). "However, the tumor recurred and analysis of the patient’s tumor cells revealed the presence, in addition to the initial PTCH1 mutation, of a mutant SMO (SMO-D473H)." (PMID 25008045, 2014). "However, loss of PTCH2 markedly affected tumor formation in combination with PTCH1 haploinsufficiency." (PMID 19032739, 2008). "Moreover, CCND1 expression is considered an early event in malignancy and its loss inhibits tumor formation in a Ptch1+/- mouse model." (PMID 18826648, 2008). "In addition, the neoplastic nature of OKC/KOT could be attributed to the mutation of PTCH1, a tumor suppressor gene causing the misregulation of the Hedgehog signalling pathway." (PMID 35096097, 2022). "Importantly, tumor‐associated astrocyte secretion of Shh drives expression of the stem cell marker nestin in Ptch1‐deficient granule neuron precursors and is indispensable for Shh MB tumorigenesis in a Smo‐dependent, but Ptch1‐ and Gli1‐independent manner." (PMID 34482626, 2022). "In NBCCS patients presenting systemic loss of one functional copy (haploinsufficiency) of PTCH1, inactivation of the normal homolog by environmental mutagenesis or random genetic rearrangement confers ligand-independent activation of the Hh pathway and tumour permissive phenotype." (PMID 34831015, 2021). "Thus, increased SMO-dependent GLI activation due to PTCH1 mutation or Shh induction might promote tumor recurrence by supporting the formation of chemoresistant CSC niches in breast tumors." (PMID 34572373, 2021). "Furthermore, in sporadic KCOT, somatic mutations of PTCH1 are often bialleic, indicating that the tumor suppressor effect of PTCH1 might be essential for KCOT development." (PMID 33066274, 2020). "Interestingly, one SHH-MB patient with a clonally dominant homozygous PTCH1 driver mutation in the primary tumor exhibited a complete switch in the oncodriver mutation in the recurrent tumor (derived from ancestral lineage with wild-type chro9q heterozygosity)." (PMID 29515801, 2018). "The finding that genetically normal stromal cells respond to Shh expressing tumors by infiltrating and supporting them heightens the importance of our observations because Ptch1/2 loss in the tumor may affect Shh sensitivity in supporting stromal cells non-cell autonomously." (PMID 27552050, 2016). "Since, the phenotypic features of patients with NBCCS may vary depending upon their ethnic origin, we asked whether crossing of Ptch1 heterozygosity into a highly tumor-susceptible genetic background could yield a mouse model that more closely duplicates the NBCCS phenotype." (PMID 26413810, 2015). "Taking advantage of the new mechanistic understanding about epigenetic inheritance, we decided to further test the hypothesis that irradiation of spermatogonia could increase cancer susceptibility in the F1 progeny using Ptch1+/− mice as a tumor-susceptible experimental model." (PMID 26452034, 2015). "Somatic analysis of a metastatic lymph node identified a pathogenic PTCH1 variant, subsequently detected at low levels (< 3% variant allele frequency (VAF)) in multiple non-tumor tissues, consistent with mosaicism." (PMID 41888819, 2026).
tumor (continued). "Several genes previously reported as subgroup-specific drivers or tumor lineage markers, such as PTCH1, PDE1C, and ST18 in SHH and OTX2, EOMS, and LMX1A in G3, were recovered and detected as DEGs exclusively in GNP and RL, respectively." (PMID 41029754, 2025). "In the Hh signaling pathway, PTCH1 is regarded as the primary regulator, and it modulates the intracellular localization of Cyclin B1, thereby linking its tumor-suppressive role to the regulation of cellular division." (PMID 40170839, 2025). "Genomic analysis of tumor samples from 1113 PM patients revealed mutations in HP genes (such as PTCH1 and SUFU), though these mutations were rare (PTCH1 at 1.2%, SUFU at 0.8%)." (PMID 40904706, 2025). "Somatic mutations associated with the hepatic fibrosis pathway included missense mutations in several COSMIC driver genes including PDGFRB (VAF = 0.020 to 0.053 in HCC tumor regions) and PTCH1 (VAF = 0.019 in HCC tumor)." (PMID 40340757, 2025). "It has been shown that Shh ligands have been identified in approximately 60% of HCC tumour tissues, and high expressions of PTCH‐1 and GLI1 mRNA have also been detected in HCC tissues." (PMID 40913253, 2025). "Consistent with this, it was shown that NeuN+ cells in SHH-MB tumors preferentially die compared to proliferating or quiescent tumor cells in a Ptch1 mutant model." (PMID 40766638, 2025). "PTCH1 is a tumor suppressor, it keeps control of the Hedgehog pathway through the autoregulative loop, as it is the transcriptional target of the pathway itself." (PMID 38731849, 2024). "Consistent with the increased penetrance and severity, the levels of Gli1, Gli2, and Sufu expression were higher in Ptch1–/+;3nSD MB tumor tissues compared with those of the Ptch1–/+ tumors, and the expression was enriched in the nucleus." (PMID 38358805, 2024). "Genomic evaluation has been performed in neoplasms from one individual with metastatic BCC; similar to other variants of BCC, an aberration of the PTCH1 gene was observed." (PMID 39429413, 2024). "The second most frequently detected protein was PTCH1, with 53.3% positive tumor samples and 76.6% positive tumor stroma." (PMID 38731849, 2024). "The PTCH1 gene is a tumor suppressor located in 9q22.3, containing 24 exons that encodes for a 12‐pass transmembrane glycoprotein called PTCH1, as well." (PMID 38287479, 2024). "Top neoantigen targets for SHH included DDX3X, PRKAR1A, and PTCH1 which are genes commonly involved in tumor progression." (PMID 39160595, 2024). "Nevertheless, cilia demonstrated tumour-suppressive activity when the Hh pathway was dysregulated downstream of SMO/PTCH1." (PMID 39234399, 2024). "Compared with littermate controls, the addition of 1 extra copy of the hSUFUSD gene increased the MB penetrance to 40% at 6 months of age, and the Ptch1–/+;3nSD MB tumor tissues appeared to have taken over the entire cerebellar volume." (PMID 38358805, 2024).